CPEB1 (cytoplasmic polyadenylation element binding protein 1)
Diseases named in the same sentence as CPEB1 in open-access papers (continued):
Sharing a sentence is not in itself a finding about the gene and the disease.
tumor (38 papers, 2014 to 2025). "CPEB1 has also been found to be implicated in cellular senescence, tumor development, inflammation, synaptic plasticity, and liver homeostasis, beyond meiosis." (PMID 34912244, 2021). "In summary, our findings revealed hypermethylation within the upstream regions of CPEB1 that was associated with its diminished expression in CRC tumours compared to para-tumour tissues." (PMID 33892791, 2021). "Thinking about the complexity of molecular mechanism in tumor, we are unable to define a cause-and-effect relationship among CASC2c, miR-101 and CPEB1 for dysfunction." (PMID 28252647, 2017). "Furthermore, CPEB1 has been implicated as a tumor suppressor in many solid tumors." (PMID 25216517, 2014). "Conversely, we observed a significant downregulation of tumor-suppressive transcriptional regulators such as CPEB1, CDH15, GFPT2, and PLA2G2A." (PMID 40950184, 2025). "Mechanistically, TUG1 recruited ALYREF to maintain the stabilization of enhancer of zest homolog 2 (EZH2) mRNA and expression of H3K27me3, repressing the transcription of the tumor-suppressor gene CPEB1." (PMID 40330150, 2024). "Our study revealed that CPEB1 is a p62 suppressor that targets protein translation, highlighting the significant function of CPEB1 as a tumor-suppressive translational regulator." (PMID 38904009, 2024). "Hypermethylation and decreased expression of CPEB1 in CRC tumour tissues were revealed by TCGA database." (PMID 33892791, 2021). "Collectively, the results of these in vitro experiments suggest that expression of CPEB1 inhibits CRC tumour cell growth, proliferation, and metastasis and promotes apoptosis." (PMID 33892791, 2021). "We validated these findings using targeted bisulfite sequencing to evaluate CPEB1 expression in tumour and para-tumour tissues collected from Han Chinese CRC patients." (PMID 33892791, 2021). "The functional characterisation presented in this study confirmed the CRC tumour suppressor function of the CPEB1 gene." (PMID 33892791, 2021). "We also demonstrated that up-regulation of CPEB1 resulted in significantly decreased tumour growth, migration, invasion, and tumorigenicity and promoted tumour cell apoptosis both in vitro and in vivo." (PMID 33892791, 2021). "Considered together, our data support the notion that the tumor suppression activities of miR-145-5p on TWIST1 translation are regulated by the fine-tuning of CPEB1 expression levels in a context-dependent manner." (PMID 33227047, 2020). "CPEB1 was shown to be a tumor-suppressor, depletion of which in mammary epithelial cells led to Epithelial-Mesenchymal-Transition (EMT) and metastatic phenotype." (PMID 31185986, 2019). "Overall, these results indicate that the upregulation of CPEB1 in HCC cells reduces tumor growth, self-renewal and chemoresistance in a mouse model." (PMID 30237545, 2018). "Cancer cell morphology was less pronounced in tumor cells expressing CPEB1 and apoptosis was increased." (PMID 30237545, 2018). "Strong CPEB1 expression was detected in few (2/61) tumor specimens and was located in the infiltration areas of tumor cells into healthy brain tissue." (PMID 27256982, 2016). "To this end, we performed methylation analyses in the promoter regions of CPEB1-4 and identified the CPEB1 gene to be hypermethylated in tumor samples." (PMID 27256982, 2016). "On the other hand, CPEB4, analogous to CPEB1, was highly expressed only in a few tumors, with tumor cells often showing strong immunoreactivity in cell processes." (PMID 27256982, 2016). "Furthermore, we investigated the relationship between this model and TME, and the results indicated that CPEB1, NOTCH3, NUAK1, and PDPK1 were strongly associated with the expression of tumor checkpoints and tumor immune infiltration." (PMID 36072578, 2022).
tumor (continued). "Moreover, although previous studies have identified components of the CPEB1 downstream signalling pathways involved in tumour suppression, the corresponding upstream regulatory events remain undefined." (PMID 33892791, 2021). "Findings available in TGCA dataset revealed significant CPEB1 down-regulation in CRC tumours." (PMID 33892791, 2021). "Our results identified a novel tumour-suppressive role of CPEB1 in CRC and found that hypermethylation of the CPEB1 promoter may lead to diminished expression due to decreased chromatin accessibility and transcription factor binding." (PMID 33892791, 2021). "We validated this finding in our sample set consisting of 46 paired CRC tumour and para-tumour tissues which revealed both the down-regulation of CPEB1 expression and the inverse correlation between transcription and CPEB1 promoter methylation (Pearson’s R = − 0.49, P < 0.0001)." (PMID 33892791, 2021). "Therefore, miR-455-5p in its wild-type form increases tumor growth and metastasis by regulating the expression of the tumor suppressor CPEB1, but has the reverse effect in its edited form." (PMID 30585209, 2018). "CPEB1 was also downregulated in human HCC tumor tissue compared with adjacent non-tumor tissue." (PMID 30237545, 2018). "Some evidences suggest a potential tumor suppressive role for CPEB1." (PMID 27142352, 2016). "Furthermore, CPEB1 appears to provide particular protection against at least one type of induced tumor formation by inhibiting tumorigenicity and decreasing angiogenic potential in vivo." (PMID 27271671, 2016). "CPEB1 was present in the infiltration areas of tumor cells into normal brain tissue." (PMID 27256982, 2016). "Deregulation of CPEB1 and CPEB4 have been linked to tumor development." (PMID 26398195, 2015). "Moreover, in tumor cells, depletion of CPEB1 disrupts this mitotic cytoplasmic regulation of poly(A) tail length, as well as pre-mRNA nuclear alternative polyadenylation site selection, and inhibits cell proliferation." (PMID 26398195, 2015). "Finally, we determined whether CPEB1 could attenuate tumor growth and chemoresistance in vivo using a mouse model." (PMID 30237545, 2018). "Our findings suggest that CPEB1 may act as a tumor suppressor for carcinoma progression." (PMID 27271671, 2016). "Thus, although both CPEB1 and CPEB4 have been linked to cell proliferation and tumor development, the evidence is conflicting as to whether they act as tumor suppressors or oncogenes based on their role in cell cycle progression." (PMID 26398195, 2015). "CPEB1 was shown to be a protein required for tumor development and may act as a tumor suppressor." (PMID 25216517, 2014). "The expression of CPEB1, p62 and NRF2 in tumor and tumor-adjacent tissues was evaluated by IHC assay." (PMID 38904009, 2024). "We found that the expression level of CPEB1 was significantly lower in the tumor tissues than in the adjacent tissues, whereas the expression levels of NRF2 and p62 were higher in the tumor tissues than in the adjacent tissues." (PMID 38904009, 2024). "The suppression of ADAR1 is linked to an increase in miR-455-5p, thus leading to a decrease in cytoplasmic polyadenylation element-binding protein 1 (CPEB1), a tumor suppressor." (PMID 38203521, 2023). "In our work, CPEB1 and COLEC12 were expressed at high levels in fibroblast-3 cells, contributing to the construction of the tumor immune microenvironment." (PMID 36131924, 2022). "To examine the DNA methylation status of the CPEB1 gene in CRC, we obtained the DNA methylation microarray dataset from TCGA database, including 387 CRC tumours and 45 samples of para-tumour tissue." (PMID 33892791, 2021).
tumor (continued). "The unedited miR-455-5p down-regulates the tumor suppressor gene cytoplasmic polyadenylation element-binding protein 1 (CPEB1), while edited miR-455-5p targets and down-regulates RHO-C, MDM4, and integrin α2, all of which have known tumor promoting functions." (PMID 33430133, 2021). "To demonstrate the anti-proliferative and anti-metastatic role of CPEB1 in vivo, we examined the levels of immunoreactive Ki67, matrix metallopeptidase-9 (MMP-9), and E-cadherin in mouse tumour tissues by immunohistochemistry (IHC) and Western blotting (WB)." (PMID 33892791, 2021). "According to literature, CPEB1 and CPEB3 act as tumor suppressors, while CPEB2 rather displays oncogenic features; in contrast, CPEB4 remains to be classified into one of these two categories." (PMID 34912244, 2021). "Taken together, our data support the notion that the tumor suppressive activity of miR-145-5p on TWIST1 translation, consequently on EMT, self-renewal, and migration, depends on the CPEB1 expression status of the cancer cell." (PMID 33227047, 2020). "Recently, several novel putative tumour suppressors such as BCL6B 16, CPEB1 17, ZNF331 18, ZNF545 19 and CHIP 20 have been identified in GC." (PMID 30714150, 2019). "In this work, we explored the characteristics and roles of CPEB1 in HCC cell lines and HCC tumor tissue." (PMID 30237545, 2018). "Analysis of CPEB1 expression in HCC showed that it was expressed at lower levels in HCC tissues and cell lines than in adjacent non-tumor tissues and normal hepatic cells." (PMID 30237545, 2018). "In mRNA expression data downloaded from TCGA, CPEB1 was found to be significantly downregulated in primary HCC tissues (normal, n = 50; primary tumor, n = 371)." (PMID 30237545, 2018). "Taken together, our findings suggest that the RNA-binding protein CPEB1 plays a potentially key role in CSC regulation and tumor growth." (PMID 30237545, 2018). "These mRNAs were expressed in a battery of normal (HPDE) and tumour (RWP-1, PANC-1 and MIA PaCa-2) pancreatic cells expressing variable levels of CPEB1 and CPEB4." (PMID 28300077, 2017). "Our study adds another potential regulatory mechanism involving microRNA, CPEB1, and IL6 within the complex microRNA-network of tumor microenvironment." (PMID 28333977, 2017). "All investigated tumor tissues (AAIII n = 6, sGBM n = 3, pGBM n = 16) revealed a significant reduction of CPEB1 transcript when compared to reference samples." (PMID 27256982, 2016). "Although the precise mechanism of tumor suppression by CPEB1 is still undetermined, we found that HES1 and SIRT1 were targets of CPEB1-mediated translational control." (PMID 25216517, 2014). "Within the tumor tissue, the expression of CPEB1, p62 and NRF2 was independent of pathological TNM stage." (PMID 38904009, 2024). "Notably, both CPEB1 and COLEC12 were expressed at significantly higher levels in fibroblasts, an essential component of the tumor microenvironment." (PMID 36131924, 2022). "Interestingly, eight among the overlapped hypermethylated genes (WT1, PAX6, GNAS, EPB41L1, CSMD1, CPEB1, RERG, and SMAD6) were previously reported to exhibit tumor suppressive functions." (PMID 34462486, 2021). "Our data indicate that favorable prognoses in PCa patients correlate with high CPEB1/miR-145p and low TWIST1 expression levels in their corresponding PCa-derived cell lines compared to cell lines established from tumor samples collected from patients with relapse." (PMID 33227047, 2020). "Moreover, the regulation is further validated in HCC tumor and peritumoral tissues, a lower level of SIRT1 protein corresponded with a higher level of CPEB1 in the same visual field of peritumoral tissues, and vice versa in the HCC tumor tissues." (PMID 30237545, 2018). "The vast majority of cells in the tumor center, in the areas of necrosis and vascular proliferation showed no CPEB1 expression." (PMID 27256982, 2016).
tumor (continued). "The vast majority of cells in the tumor center, in the areas of necrosis and vascular proliferation showed no CPEB1 expression, suggesting that expression of CPEB1 is silenced along with progression of cancer." (PMID 27256982, 2016). "Taken together, these results suggest that CPEB1 is a potential tumor suppressor and lack of CPEB1 potentially increases susceptibility to cancer." (PMID 25216517, 2014). "Tumor cells in control mice were positive for Nestin expression, but no signal was detected in mice injected with CPEB1-overexpressing GSCs." (PMID 25216517, 2014). "Interestingly, the expression of CPEB1 was negatively correlated with the expression of p62 in the tumor (R=-0.241, P<0.05), but was not correlated with the expression of NRF2." (PMID 38904009, 2024). "We found significantly higher levels of methylation of the CPEB1 upstream region (located at chr15:83316804–83316986), which is a region close to the CPEB1 promoter (chr15:83316688–83316747), in CRC tumours than that in the accompanying para-tumour tissues (P < 0.0001)." (PMID 33892791, 2021). "Similarly, the specific APA modification of VEGFB may be involved in the functional regulation of CPEB1 and CPEB4, further contributing to the tumorigenesis of multiple tumor types, including cervical, ovarian, and glioma cancers." (PMID 32626751, 2020).
cancer (27 papers, 2010 to 2024). A tumor composed of atypical neoplastic, often pleomorphic cells that invade other tissues. "These CPEB1-deficient cancer cells exhibited remarkably higher resistance to various ferroptosis inducers than their CPEB1-normal counterparts, as identified by CCK-8 and colony formation assays." (PMID 38904009, 2024). "We found that CPEB1 deficiency in cancer cells promotes the translation of p62/SQSTM1 by facilitating mRNA polyadenylation." (PMID 38904009, 2024). "Cytoplasmic polyadenylation element-binding protein 1 (CPEB1), a sequence-specific RNA-binding protein that regulates mRNA polyadenylation and translation, has been linked to cancer progression and metastasis." (PMID 30237545, 2018). "Reduced levels of CPEB1 are associated with several types of cancer, cell invasion and angiogenesis." (PMID 30237545, 2018). "Moreover, CPEB1 is closely associated with the prognosis of malignant tumors in clinic, as demonstrated by our study and published open data, suggesting that it has the potential to be developed into a clinical biomarker or a therapeutic target." (PMID 38904009, 2024). "A reduction of CPEB1 expression is associated with the progression of various cancers." (PMID 30237545, 2018). "Importantly, our data also suggest that loss of CPEB1 expression may be required to allow cancer cells to proceed to a metastatic stage with the acquisition of stem cell traits." (PMID 33227047, 2020). "Cytoplasmic polyadenylation element-binding protein 1 (CPEB1), a sequence-specific RNA-binding protein that regulates polyadenylation and mRNA translation, is associated with cancer progression and metastasis." (PMID 38329726, 2024). "The expression and function of CPEB1 have garnered considerable attention due to its diverse expression patterns and roles across various types of cancer." (PMID 38994352, 2024). "Overall, recent research has increasingly recognized the multifaceted role of CPEB1 in cellular processes and its impact on various cancers." (PMID 38994352, 2024). "CPEB1 is reported to regulate oocyte maturation, cancer progression, cell cycle, and neural development by controlling translation of various transcripts." (PMID 35177647, 2022). "Regarding cancer progression, CPEB1 has been shown to regulate epithelial‐to‐mesenchymal transition by modulating zona occludens 1 mRNA localization and regulating the translation of matrix metalloproteinase 9 mRNA in mammary epithelial cells." (PMID 34480525, 2022). "We also assessed the possibility that CPEB1 directly regulates sirtuin 1 (SIRT1) to mediate cancer stemness in HCC through an interaction with a CPE site." (PMID 30237545, 2018). "Our results indicate that the expression of CPEB1 in CSCs was negatively correlated with cancer progression, which is similar to results in other cancers." (PMID 30237545, 2018). "To conclude, we analyzed the influence of CPEB1 on cancer stemness in HCC cells by analyzing self-renewal ability, chemoresistance, metastasis and expression of the stem cell-related genes OCT4, NANOG, SOX2, LIN28, CD24, EpCAM and CD133." (PMID 30237545, 2018). "In this study, we have demonstrated that CPEB1 directly regulates sirtuin 1 (SIRT1) mRNA to mediate cancer stemness in HCC." (PMID 30237545, 2018). "Alteration of individual cancer relevant signaling pathways upon CPEB1 overexpression was investigated by a cell based reporter assay." (PMID 27256982, 2016). "The highest level of CPEB1 mRNA is observed in the reproductive system and brain, with reduced expression of CPEB1 mRNA in cancers of these tissues." (PMID 25216517, 2014). "CPEB1, the founding member of this family, has become an important model for illustrating general principles of translational control by cytoplasmic polyadenylation in gametogenesis, cancer etiology, synaptic plasticity, learning, and memory." (PMID 38628584, 2024).
cancer (continued). "As CPEB1 is involved in cancer progression and therapeutic resistance 12, 14, we wondered whether its expression level is altered in the majority of cancer types." (PMID 38904009, 2024). "Thus, CPEB1 loss-induced p62 upregulation remarkably improves NRF2 proteostasis, which benefits cancer cells from antioxidative stress and ferroptosis resistance." (PMID 38904009, 2024). "Complementarily, overexpression of CPEB1 sensitized cancer cells to ferroptosis inducers." (PMID 38904009, 2024). "However, we know considerably less about CPEB3’s role in cancer development compared with the body of work available for CPEB1 and CPEB4." (PMID 33146632, 2020). "Finally, the human counterpart microRNAs of mmu-miR-5112 that regulate the CPEB1 expression in cancer microenvironments should be investigated in future studies." (PMID 28333977, 2017). "Therefore, overexpression of CPEB1 abrogates cancer stemness and chemoresistance in HCC." (PMID 34480525, 2022). "We confirmed the inverse correlation between CPEB1 expression and methylation of its promoter in the SW480 and HCT116 CRC cancer cell lines that were treated with the methylation inhibitor, 5-Aza-dC (5-aza-2′-deoxycytidine, DAC)." (PMID 33892791, 2021). "In this study, we found that CPEB1, a CPE-binding protein involved in the regulation of mRNA translation, negatively mediates HCC cancer stemness and chemoresistance in vitro and in vivo." (PMID 30237545, 2018). "Overall, our findings suggest that the negative regulation between CPEB1 and SIRT1 contributes to the suppression of cancer stemness in HCC." (PMID 30237545, 2018). "MiR-101 exercises its biological function in multiple cancer types by interating with CXCR7, CDK8, EZH2 level and CPEB1." (PMID 27911279, 2017). "The shared mRNAs between T2DM and BC were enriched in cytochrome (CYP) pathways, and further analysis of CPEB1 and COLEC12 expression in cell lines, single cells and other cancers showed that they were strongly correlated with the survival and prognosis of patients with BC." (PMID 36131924, 2022). "The intensities of CPEB1 immunostaining were moderately positive, weakly positive and negative in cancer samples, stronger staining was observed in peritumoral tissues." (PMID 30237545, 2018). "Using site-directed mutagenesis, a luciferase reporter assay, and immunoprecipitation, we found that CPEB1 could directly target the 3′-UTR of SIRT1, control poly(A) tail length and suppress its translation to mediate cancer stemness in vitro and in vivo." (PMID 30237545, 2018). "Moreover, CPEB1 appears to regulate the polyadenylation and translation of SIRT1 to mediate cancer stemness in vitro and in vivo." (PMID 30237545, 2018). "However, the involvement of CPEB1 in HCC remains unclear, and its roles in HCC cancer stemness, self-renewal and chemoresistance is yet to be elucidated." (PMID 30237545, 2018).